CCL2 (C-C motif chemokine ligand 2)
Diseases named in the same sentence as CCL2 in open-access papers (continued):
Sharing a sentence is not in itself a finding about the gene and the disease.
tumor (continued). "This work demonstrates that although the chemokine crosstalk in the tumor microenvironment (TME) is a complex and overall poorly understood process, both the CCL2:CCR2 and CCL5:CCR5 ligand/receptor pairs have been identified as likely therapeutic targets across several types of cancers." (PMID 27852031, 2016). "CCL2 together with CCL5 were shown to play an important role in breast malignancy and to mediate many types of tumor-promoting cross-talks between the tumor cells and cells of the tumor microenvironment." (PMID 26759169, 2016). "Of interest, we found that the corresponding receptors of SDF-1α and CCL2, CXCR4 and CCR2 were up-regulated in the THP1 cells, which might amplify the chemotaxis of monocytes into the tumor sites." (PMID 27888616, 2016). "CCL2 and CCR2 positive staining were mainly located in the cytoplasm of the tumor cells." (PMID 27409666, 2016). "Since RT increases intratumoral CCL2/CCL5 creating a positive chemoattractant gradient in the TME and facilitating migration of IM into the tumor, CVC may also interfere with the extravasation of IM from the blood stream into the tumor." (PMID 27852031, 2016). "Additionally, signal molecules produced by tumor cells, such as lactate, HRG/PIGF, chemokine ligand 2 (CCL2), soluble colony-stimulating factor 1 (sCSF1), and POSTN, play critical roles in macrophage polarization." (PMID 27683110, 2016). "We found that the number of circulating EPCs increased in tumor-bearing mice compared to tumor-free mice and that disruption of Ccl2 and Ccr2 had profound effects on circulating EPC numbers: EPCs were greatly reduced in Ccl2-/- mice and increased in Ccr2-/- mice." (PMID 27820834, 2016). "WT8/CCL2 and WT8 mock cells were subcutaneously implanted into mice and tumor growth was monitored." (PMID 27666332, 2016). "CCL-2, 3, 4, and CXCL-9 and 10 were induced in both SUM149 and DU145 tumors; which collectively, may enable the recruitment of immune cells into the tumor." (PMID 27806313, 2016). "However, low level CCL2 secretion, with physiological accumulation of TAM, promoted tumor formation." (PMID 27191744, 2016). "Inactivation of NF-κB, STAT3, or HIF-1α, neutralization of CCL2 or CXCL12, or TAM depletion results in disrupted angiogenesis and decreased tumor growth, highlighting the critical role of inflammatory mediators in tumor angiogenesis." (PMID 26501341, 2015). "Thus, our data indicated that MOs were attracted to the MM tumor bed by chemokines CCL3, CCL14 or CCL2 because the process was significantly attenuated by antibodies directed against these chemokines." (PMID 26155942, 2015). "Our study presented that CCL2 had a negative correlation with lymph node staging; however, its role in tumor prognosis has not yet been determined." (PMID 26313265, 2015). "Monocyte chemotactic protein-1 (MCP-1/CCL2) is an important immune factor, which may be important in cancer progression by promoting proliferation, invasion, metastasis and the tumor microenvironment." (PMID 25695619, 2015). "In the same line, the chemokines CCL2 or CCL25 produced by cancer cells could be attractant for MSCs and explain their tropism for tumor sites." (PMID 26362269, 2015). "However, when we compared the expression of the chemokine genes in MM BM (5TGM1 tumor-bearing mice) versus tumor-free BM, we found that CCL3 and CCL2 expression was higher in MM BM (p < 0.01)." (PMID 26155942, 2015). "Cancer cells aberrantly secrete a whole battery of growth factors and chemokines such as CCL2 and CCL5 to recruit macrophages to the tumor microenvironment where they are stimulated to mature and secrete further bioactive molecules to aid processes crucial for cancer development and metastasis." (PMID 26375811, 2015). "In our study, CCL2 orchestrates CCR2-expressing immunomodulatory cells including Tregs, MDSCs and TAMs in the tumor microenvironment, and generates DCregs partly in collaboration with LCN2 that is released from the CCL2-stimulated tumor cells." (PMID 25883937, 2015).
tumor (continued). "CCL2 (MCP1) is a cognate ligand for chemokine receptor CCR2, which is expressed by monocytes in peripheral blood and plays multiple roles in cancer, including chemoattraction of circulating CCR2-positive monocytes/macrophages to the tumor vicinity." (PMID 25978454, 2015). "NF-κB may promote the tumor formation and progression through up-regulation of its downstream effectors including TGF-β, IL-10, CCL2, COX-2, VEGF and CCL22." (PMID 26683520, 2015). "Importantly, prevailing among all the different molecules that were identified in the co-culture of the three cell types was CCL2, followed by IP-10 (CXCL10) and IL-6, confirming the central role of these molecules in this tumor model." (PMID 25599228, 2015). "Mechanically, TAMs are generally recruited from blood monocytes by diverse chemokines such as CCL2 (MCP-1), CCL5, CCL7, CXCL8 and CXCL12, migrate to diverse areas of the tumor microenvironment and differentiate according to surrounding cellular or environmental stimuli." (PMID 25685069, 2015). "Moreover, at the tumor site, the IL-1 and IL-6 cytokines, the S100A8 and S100A9 pro-inflammatory proteins, the chemo-attractant molecules CCL2, SDF1 and CXCL5 are the main factors responsible for the recruitment and the induction of MDSCs." (PMID 28536400, 2015). "In both mixed cultures (C4-2 tumor cells plus WPMY-1 myofibroblasts, and C4-2 tumor cells plus THP-1 TAM-like cells), enzalutamide induced CCL2 and etanercept blocked CCL2 induction, consistent with our proposed paracrine mechanism." (PMID 26327448, 2015). "However, as well as CCL2, ANGPT2 has been demonstrated to promote tumor growth indirectly via increase of TIE2+ TAM-like macrophages in the tumor microenvironment." (PMID 25883937, 2015). "Other studies report that expression of CCL2 and CXCL12 may originate from stromal cells and regulate tumor cell behavior through promotion of paracrine signaling." (PMID 24970800, 2014). "Surprisingly, the nitrated/nitrosylated CCL2 does not lose the ability to recruit MDSCs to the tumor, likely due to higher expression of CCR2 in myeloid than in T cells." (PMID 24605112, 2014). "In CCL2 (−/−) mice, neoplasms that grew failed to accumulate dendritic cell-like APCs in response to chemotherapy." (PMID 25257976, 2014). "CCL2, CXCL1, and IL6, produced by 18Co cells could contribute to increased STAT1 activity in tumor cells." (PMID 24818101, 2014). "Transcripts of other genes such as chemokine ligand-2 (Ccl2) and chemokine receptor-4 (Cxcr4) were not affected in bone marrow by tumor ablation." (PMID 24270800, 2014). "A slight, but significant increase in tumor size in the CCR2−/− mice compared to wild-type littermates was detected at the 44-week time point, which is consistent with the poorer survival observed in human NSCLC patients with low-CCL2 expression." (PMID 25505466, 2014). "Cancer cells recruit monocytes, macrophages and other inflammatory cells by producing abundant chemoattractants and growth factors, such as macrophage colony-stimulating factor (M-CSF/CSF-1) and monocyte chemoattractant protein-1 (MCP-1/CCL2), to promote tumor growth and dissemination." (PMID 23549262, 2013). "MYCN was found to down-regulate CCL2 expression, thus providing a mechanistic insight into the different composition of tumor-infiltrating lymphocytes in MYCN amplified vs. MYCN non-amplified high risk tumors." (PMID 23805414, 2013). "Celecoxib treatment reduced CCL2 and increased CXCL10 production, recruiting CTL to the tumor site." (PMID 24202450, 2013). "Chemokines such as CCL2 and CCL4 could help recruit transferred T cells to the primary tumor site and thereby prevent tumor recurrence, and inflammatory cytokines like IL-6 can promote effector T cell infiltration of distant tumor sites." (PMID 23935927, 2013).
tumor (continued). "As a result of TNFα + Estrogen + EGF stimulation, new cell subtypes have dominated the tumor cell population, expressing high levels of VLA6 and of the metastasis-related adhesion molecules CD44 and β1, accompanied by high levels of CXCL8, CCL2, and MMPs that were released by the cells." (PMID 24369447, 2013). "CCL2 can also directly induce angiogenesis in endothelial cells, which express its receptor, CCR2, and induce VEGF and hypoxic-inducible factor (HIF)-1 in tumor cells." (PMID 23847541, 2013). "At day 12 post-tumor cells (day 42 post-BMT), a clear-cut bioluminescent signal increase was evident over the chest of IgG2a-treated controls, but was significantly suppressed in anti-CCL2/12-treated mice (images on the right and graphs)." (PMID 23967166, 2013). "In HCC, tumor cells have been demonstrated to recruit and activate TAMs by secretion of Vascular Endothelial Growth Factor (VEGF), Platelet-derived Growth Factor (PDGF), TGF-β, CCL2, or M-CSF." (PMID 23533994, 2013). "Ex vivo incubation of isolated tumor cells with EGCG inhibited the CSF-1 and CCL-2 expression." (PMID 24044575, 2013). "We further show that the administration of CCR2-Ig, that selectively and specifically neutralize CCL2, to mice in which CCR2 is expressed only on tumor cells, further suppressed tumor development, implicating for the key role of this chemokine supporting tumor survival in an autocrine manner." (PMID 22279523, 2012). "CCL2 and CCL5 have been shown to promote tumor cell migration and invasion." (PMID 23056468, 2012). "Several CC chemokine members, including CCL2 (MCP-1), CCL3 (MIP-1α), CCL5 (RANTES), CCL7 (MCP-3), CCL8 (MCP-2), CCL17 (TARC) CCL 20 (MIP-3α), CCL22 (MDC) and CCL23 (MPIF-1), are produced mainly by tumor infiltrating lymphocytes (TIL) and monocytes, and some of them also by cancer cells." (PMID 24213462, 2012). "Moreover, when developed subcutaneously, tumor induced the deposition of a CCR2 ligand, CCL2 inside IVRs, resulting in the enhancement of antigen uptake by intrathymic Sirpα+ cDCs." (PMID 22815949, 2012). "PDAC tumors have been shown to express high levels of CXCL12 and CCL2, which could promote PDC migration into the tumor." (PMID 22190968, 2011). "Significant associations were found between CCL2 & CCL5 and TNFα & IL-1β in the tumor cells in DCIS and IDC-no-relapse patients." (PMID 21486440, 2011). "Whereas in mouse models c-fms inhibitors, anti-CCL2 monoclonal antibodies, or bisphosphonates can be given before, or simultaneously, with inoculation with tumor cells, in humans this is not the case." (PMID 22162712, 2011). "The TCM components CCL2, CXCL1, CXCL5 and VEGF seem to play a role in modulating the inflammatory response through inhibition of IL-12p70 secretion by DCs, possibly to protect the tumour from a potent immunologic response against it." (PMID 22125641, 2011). "In addition, the interaction of the bone and tumor cells results in distinct regulation of the chemokine, MCP-1/CCL2, and is dependent on an 'intact' microenvironment." (PMID 19192289, 2009). "Furthermore, tumor tissue analysis showed that CCL2 and HIF‐1α expression levels were higher in the HFD group than in the CD group under IgG treatment, highlighting the role of the FA/HIF‐1α/CCL2 axis in cancer." (PMID 41160815, 2026). "Inflammatory monocytes, which highly express CCR2 and respond to CCL2 produced by tumor and stromal cells, are recruited to metastatic sites such as the lungs and liver before tumor cells and differentiate into MAMs, secreting VEGF and promoting tumor cell metastasis." (PMID 41341593, 2025). "Notably, CCL2 can originate from other stromal cells within the TME, in addition to tumor cells." (PMID 40756366, 2025). "Furthermore, CAFs may alter the anti‐tumor immune response through secretion of several immune modulators such as IL6, CCL2, CXCL12, and TGFβ2, which we found to be up‐regulated in CMS4 PM." (PMID 39739693, 2025).
tumor (continued). "CAAs secrete chemokine ligands CCL2 and CCL5, interleukin-1 (IL-1), interleukin-6 (IL-6), tumor necrosis factor-α (TNF-α), and vascular endothelial growth factor (VEGF), and promote cell aggressiveness, tumor progression, migration, and chemotherapy resistance." (PMID 40141437, 2025). "This reprogramming enhances the secretion of M1-type chemokines (e.g., CCL2, CCL3, CCL4, CCL5, CXCL1, CXCL10, and CCL22), which in turn promotes the infiltration of various immune cells, including CD8+ T cells, NK cells, and mature dendritic cells (cDCs), into the tumor microenvironment." (PMID 41002423, 2025). "Importantly, despite the slight reduction in Ccl2 expression, PyMT-RIDad mice still demonstrated the recruitment and accumulation of TAMs, indicating that TAM recruitment emerges as a critical factor influencing early tumor growth." (PMID 40526430, 2025). "The chemokines CCL2 and CCL5 well known attractants of CTLs as well as CXCL9 and CXCL10 powerful chemoattractants of activated CTLs were all highly induced by mIL12 mRNA treatment in both models and likely laid the ground for trafficking and retention of these effectors deep within the tumor cores." (PMID 40321762, 2025). "The chemokines CCL2 and CCL5 well known attractants of CTLs as well as CXCL9 and CXCL10 powerful chemoattractant of activated CTLs were all highly induced by mIL12 mRNA treatment in both models and likely laid the ground for trafficking and retention of these effectors deep within the tumor cores." (PMID 40560386, 2025). "Monocyte chemoattractant protein-1 (CCL2/MCP-1), CXCL1, CXCL8, and other chemokines elevated during systemic inflammation recruit myeloid-derived suppressor cells (MDSCs), macrophages, and neutrophils to the prostate microenvironment, collectively promoting tumor growth and immune evasion." (PMID 41555998, 2025). "MSC recruitment to tumor sites is facilitated through numerous factors secreted by stroma, including growth and angiogenic factors (PDGF, FGF, VEGF, SDF, HGF), chemokines, and inflammatory cytokines (CCL2, CCL5, CCL22 and CXCL12, TNFα, TGFβ, IL-1β, IL-6, IL-8)." (PMID 40723180, 2025). "Starting from the fact that an expanded expression of CCL2 was observed in tumor-assaulting macrophages, not in DLBCL cells, it was presumed that DE-DLBCL cells could produce CCL2 and influence CCR2-expressing macrophages." (PMID 40426926, 2025). "Moreover, among typical cytokines produced following STING activation, CCL2 fold change was the one that increased the most in the serum of B16-F10-bearing mice and differentiated the observed response to the STING agonist between investigated tumor models." (PMID 39857957, 2025). "Mechanistically, SPON2 enhances interleukin 10 (IL10), C-C motif chemokine ligand 2 (CCL2), and colony stimulating factor 1 (CSF1) secretion, drives M2 macrophage polarization, and activates the NF-κB/VEGF signaling axis to facilitate EMT and tumor progression." (PMID 40730813, 2025). "In the early stages of tumor progression, the presence of cDC1s in the TME is limited due to the preferential recruitment of tumor‐promoting immune cells by chemokines such as C‐X‐C motif chemokine ligand 1 (CXCL1), C‐C motif chemokine ligand 2 (CCL2), and CCL20, which are secreted by tumor cells." (PMID 40667699, 2025). "Nanostring data from BRD4 inhibitor–treated tumors also revealed decreased tumor expression of chemokines important for MDSC recruitment to tumors including CXCL5, CXCL3, and CCL2, suggesting that the reduced intratumoral MDSC levels could be caused by impaired MDSC migration into the TME." (PMID 40762981, 2025). "In the early stages, SASP components such as IL-6, IL-8, and CCL2 recruit immune cells to eliminate damaged cells, but prolonged SASP signaling alters this equilibrium, driving chronic inflammation, suppression of immune responses, and ECM remodeling, thereby facilitating tumor development." (PMID 41463272, 2025).
tumor (continued). "Cisplatin-triggered ferroptotic tumor cells reprogram TANs toward an N1-like phenotype, characterized by the upregulation of cytotoxic effectors such as TNF-α, granzyme B, and NE, as well as chemokines and cytokines including CCL2, CCL3, CXCL9, CXCL10, CXCL11, IL-12A, and IL-12B." (PMID 40805288, 2025). "To further verify the relationship between IL34 and tumor cells, we localized tumor subgroups in the spatial transcriptome and found that the spatial location of the tumor with high IL34 expression was close to the TNF-α+ TAMs with high TNF and CCL2 expression." (PMID 39865310, 2025). "As we expected, the flow cytometric results showed that Ly6Chigh monocytes and neutrophils markedly infiltrated in tumour tissues of oxPAPC‐treated WT mice, while there was no significant change in oxPAPC‐treated CCL2−/− mouse or LTB4R−/− mice compared with that in their respective control mice." (PMID 37905494, 2024). "MuRF1 expression could also depend on CCL2 concentrations; intramuscular doses of CCL2 may not reflect tumor-derived CCL2 levels in the muscle." (PMID 38973385, 2024). "Therefore, given the upregulated secretion of CCL2 and LTB4 in response to oxPAPC treatment, we aimed to investigate the possible mechanisms through which these cytokines promote the infiltration of MDSCs into tumour tissues." (PMID 37905494, 2024). "Thus, intramuscular injection of CCL2 does not completely model the effects of tumor derived CCL2 on muscle." (PMID 38973385, 2024). "CSCs are crucial for monocyte recruitment across tumor types; supernatants from cholangiocarcinoma, hepatocellular carcinoma, or glioblastoma cells under CSC-enriched conditions show elevated levels of tumorigenic macrophage factors like CCL2, CCL5, CSF1, GDF15, IL-13, TGFβ, periostin, and WISP1." (PMID 39068459, 2024). "However, CCL2 KD did not affect tumor cell growth in vitro, indicating that CCL2 was the key molecular mediator to modulate innate immunity in favor of the IBC tumor development and aggressiveness." (PMID 38786066, 2024). "Furthermore, M2 macrophages contribute to tumor progression by remodeling the TME through the release of matrix metalloproteinases (MMPs) such as MMP2, 7, 9, and 12, inducing angiogenesis via VEGF secretion, and recruiting Tregs through CCL2 production." (PMID 38785789, 2024). "For example, the blocking of CCL2 can inhibit metastasis of tumors and interrupt the CXCR4/CXCL12 chemokine axis, which can be used to sensitize drug-resistant tumor cells to chemotherapy or radiotherapy and may inhibit angiogenesis and proliferation of tumor cell." (PMID 38578317, 2024). "Surprisingly, treatment with an anti-CCL2 antibody of KPC tumors treated with MEK and CDK4/6 inhibitors, along with an EZH2 blockade, led to a significant reduction in anti-tumor effects, highlighting that NK cell accumulation was critical for tumor regression." (PMID 38339310, 2024). "Tumor cells initiate recruitment of monocyte-derived circulating macrophages by production of Colony Stimulating Factor 1 (CSF1) and CC chemokine Ligand 2 (CCL2), leading to their binding to CSF1 receptor (CSF1R) and CCL2 receptor (CCR2) on the macrophage cell surface." (PMID 39660126, 2024). "Furthermore, the adaptive deletion of PTEN in brain metastatic tumor cells leads to increased secretion of chemokine CCL2, which recruits microglia expressing CCL2 receptor (CCR2) to mutually promote the growth of brain metastatic tumor cells by enhancing proliferation and reducing apoptosis." (PMID 37307835, 2024). "The expression levels of ccl-2 (MCP-1), ccl-20 (MIP-3), ccl-7 (MCP-3), CXCL-4 (PF-4), CXCL 1 (Gro -), and CXCL-12 (SDF-1) are also significantly increased in replicative senescent cells, allowing the disruption of the blood-tumor barrier integrity and greater spread of tumor cells." (PMID 37450933, 2024).